MYBPC3 (myosin binding protein C3)
Diseases named in the same sentence as MYBPC3 in open-access papers (continued):
Sharing a sentence is not in itself a finding about the gene and the disease.
cardiac hypertrophy (continued). "Here, AZD2014 is examined in in vitro model of phenylephrine (PE)-induced human cardiomyocyte hypertrophy and a myosin-binding protein-C (Mybpc3)-targeted knockout (KO) mouse model of cardiac hypertrophy." (PMID 34674743, 2021). "As a dual mTOR kinase inhibitor, AZD2014 demonstrates preventive effects against PE-induced cardiac hypertrophy in vitro and Mybpc3-related HCM phenotypes in vivo." (PMID 34674743, 2021). "Our observation of systemic metabolic disturbances in Mybpc3−/− mice due to cardiac hypertrophy may help identify new biomarkers or therapeutic targets that address not only the heart but also the systemic metabolic consequences of cardiac dysfunction." (PMID 41155405, 2025). "Finally, 1-day-old homozygous Mybpc3-targeted knock-in mice treated with AAV9–Mybpc3 demonstrated increased total protein levels of myosin binding protein C (MyBP-C) and prevention of cardiac hypertrophy development." (PMID 39499917, 2025). "Overall, Foxo6os could interact with MYBPC3 to potentially mediate the process of cardiac hypertrophy." (PMID 40548957, 2025). "A single systemic administration of AAV9-MYBPC3 in 1-day-old KI mice prevented the development of cardiac hypertrophy and dysfunction during the observation period of 34 weeks and increased MYBPC3 messenger RNA (mRNA) and MYBPC3 protein levels in a dose-dependent manner." (PMID 38540296, 2024). "Moreover, the loss of cMyBP-C protein results in left ventricular dilation, cardiac hypertrophy and impaired ventricular function in Mybpc3 null mice." (PMID 36357371, 2022). "Our results demonstrate that cardiomyocytes treated with AZD2014 retain the normal phenotype and AZD2014 attenuates cardiac hypertrophy in the Mybpc3-KO mouse model through inhibition of dual mTORC1 and mTORC2, which in turn results in the down-regulation of the Akt/mTOR signaling pathway." (PMID 34674743, 2021). "Generally, the phenotype of subjects with MYBPC3 mutations is variable, and cardiac hypertrophy usually does not manifest until early adolescence with penetrance increasing with age and peaking at approximately 60 years of age." (PMID 26267065, 2015). "In addition, 26.7% of carriers of the pLOF variant in the MYBPC3 gene without a diagnosis of HCM had clear features of myocardial enlargement or hypertrophy in echocardiography." (PMID 37686045, 2023). "Most patients with MYBPC3-related HCM present with a later age of onset and less severe myocardial hypertrophy." (PMID 41561115, 2025). "In vivo, the Mybpc3-KO mouse model given AZD2014 to dually inhibit mTORC1/2, revealed that mTOR is involved in the regulation of cardiac hypertrophy and in the control of vital cellular processes necessary for maintenance of cardiac function." (PMID 34674743, 2021). "This suggests that the RER metabolic expenditure differences observed in Mybpc3−/− mice are not due to differences in physical activity levels but rather an inherent systemic metabolic shift due to cardiac hypertrophy." (PMID 41155405, 2025). "Knock-in mice for a truncated form of Mybpc3, one of the most commonly mutated disease-causing genes of HCM, in fact did not develop spontaneous cardiac hypertrophy." (PMID 37435054, 2023). "Studies have revealed that MYBPC3 +/− mice are indistinguishable from wild-type control mice whereas MYBPC3 −/− mice exhibit significant cardiac hypertrophy." (PMID 22529996, 2012).
dilated cardiomyopathy (27 papers, 2008 to 2025). "Complexities exist in genotype-phenotype relationships, in relating MYBPC3 variant change in causing dilated cardiomyopathy." (PMID 38586174, 2024). "MYBPC3 has garnered much attention over the past several decades due to its prevalent mutational rate leading to congenital hypertrophic and dilated cardiomyopathy." (PMID 27683561, 2016). "Similar mice with homozygous Mybpc3 gene mutations created by other researchers have been shown to develop dilated cardiomyopathy coupled with myocyte hyperplasia post-natally due to an extra round of postnatal cell division." (PMID 27323879, 2016). "The cardiac isoform, encoded by MYBPC3, has been extensively studied over the last several decades due to its high mutational rate in congenital hypertrophic and dilated cardiomyopathy." (PMID 27683561, 2016). "For example, mutations in the genes encoding cardiac β-myosin heavy chain (MYH7) or cardiac myosin-binding protein C (MYBPC3) are known to cause hypertrophic and dilated cardiomyopathies." (PMID 25528061, 2014). "Genetic mutations contribute to 30-40% of dilated cardiomyopathy (DCM) and HCM cases, with titin truncating variant (TTNtv), myosin-binding protein C3 (MYBPC3), lamin A/C gene (LMNA) and BCL2-associated athanogene-3 (BAG3) among the most common pathogenic variants." (PMID 40313442, 2025). "MYBPC3 is the primary gene known to cause restrictive cardiomyopathy, dilated cardiomyopathy, and left ventricular non-compaction." (PMID 37445689, 2023). "In addition to HCM, identical MYBPC3 mutations can lead to left ventricular noncompaction and to restrictive or dilated cardiomyopathy." (PMID 37445689, 2023). "Further, truncating variants in MYBPC3 have only been associated with HCM and not primary dilated cardiomyopathy." (PMID 32163302, 2020). "Notably, alterations in the MYBPC3 gene have been primarily associated with HCM but can also be associated with other types of heart muscle disease, including dilated cardiomyopathy, restrictive cardiomyopathy, and left-ventricular non-compaction." (PMID 36615026, 2022).
atrial fibrillation (11 papers, 2018 to 2025). A disorder characterized by an electrocardiographic finding of a supraventricular arrhythmia characterized by the replacement of consistent P waves by rapid oscillations or fibrillatory waves that vary in size, shape and timing and are accompanied by an irregular ventricular response. "Of the individuals with MYBPC3 p.(Gln1061*) variant, 26% presented syncope/pre-syncope, 23% had either chronic or paroxysmal atrial fibrillation, 9% have had sustained VT or ventricular fibrillation and 26% had family history of SCD." (PMID 30235249, 2018). "We can see that the LA_d, atrial fibrillation, age, mutation MYBPC3, and LVIDs features contributed to the increase in the predicted value for LA_d over time, while the LA_Vol and mutation MYH7 features contributed to the decrease in the predicted value for LA_d." (PMID 35107432, 2022). "For example, patients with PV in MYH7 have a higher incidence of atrial fibrillation, earlier age of onset, and more severe disease compared to those who carry PV in the MYBPC3 gene." (PMID 38540296, 2024).
Ventricular arrhythmia (10 papers, 2019 to 2025). "In 24 mice models ventricular arrhythmias were reported, most frequently in models with sarcomere mutations: Tnnt2 (n = 10 [41.7%]), Myh6 (n = 4 [16.7%]), and Mybpc3 (n = 3 [12.5%])." (PMID 40306862, 2025). "A recent meta‐analysis reported that myosin the MYH7 mutation group showed the highest rate of ventricular arrhythmia compared with the MYBPC3, TNNT2, and TNNI3 mutation group." (PMID 32815161, 2020). "Moreover, those with splice donor mutations in the MYBPC3 gene were more susceptible to ventricular arrhythmias (even before the phenotypical HCM manifests) compared to those with frameshift and nonsense mutations." (PMID 38540296, 2024). "However, a recent investigation of Japanese patients showed that HCM cases with the MYBPC3 mutation may have a high frequency of ventricular arrhythmia and syncope." (PMID 30959811, 2019). "When excluding the more prevalent TNNT2 and MYBPC3 variants in HCM G+P− individuals, the occurrence of ventricular arrhythmias (OR 1.72 [95% CI 0.44;4.89], P=0.306) and atrial arrhythmias (OR 1.43 [95% CI 0.84;2.32], P=0.156) was comparable to G−P− controls." (PMID 36264615, 2022). "Also, TNNI3 mutation carriers have lower survival than MYBPC3 and MYH7 mutation carriers, and TNNC1 mutation carriers have a higher risk of developing fatal ventricular arrhythmias." (PMID 38540296, 2024). "Ventricular arrhythmias were induced in 17 studies and occurred spontaneously in 7 studies, of which 3 studies reported on sarcomeric mutations (Tnnt2 [F110I, I79N, R92Q] and Mybpc3 [KI]) and 4 on nonsarcomeric mutations." (PMID 40306862, 2025). "In addition, the genotype–phenotype relationship in PLN patients is not distinctly different from those caused by other causal genes (MYBPC3/MYH7), but these patients could carry a high risk for ventricular arrhythmia." (PMID 38392255, 2024). "The C-terminal truncated Mybpc3 mice also developed fibrosis by 3 months and myocardial disarray and ventricular arrhythmias at 30 to 55 weeks, conditions that were absent in the heterozygous mice." (PMID 40306862, 2025).
Arrhythmia (9 papers, 2021 to 2025). Any cardiac rhythm other than the normal sinus rhythm. "The study of Italian patients with HCM and MYBPC3(NM_000256.3):c.913_914del showed a higher disease penetrance in males and a higher frequency of arrhythmias compared to patients with other likely pathogenic and pathogenic (LP/P) MYBPC3 variants." (PMID 39160446, 2025). "Most of these variants were located in genes associated with inherited arrhythmias and arrhythmic cardiomyopathies, such as MYBPC3, KCNQ1, TTN, CASQ2, GPD1L, DPP6, HCN4 and NEXN." (PMID 36008935, 2022). "CMs with mutations in Tnnt2 (R92Q) demonstrated spontaneous calcium waves and transients, burst contractions or extreme relaxation prolongations were found in Mybpc3 KI CMs,82 and CMs showed arrhythmia after isoproterenol administration." (PMID 40306862, 2025). "It must be noted that several patients with symptomatic and severe HCM carrying p.Gln1233Ter of MYBPC3 also have arrhythmias." (PMID 36555486, 2022).
left ventricular hypertrophy (9 papers, 2015 to 2025). Enlargement of the LEFT VENTRICLE of the heart. "The training cohort focused on obstructive HCM, the most prevalent symptomatic subtype, with genetic specificity controlled by an independent MYBPC3 truncation mutation subgroup and secondary hypertrophy excluded by ruling out aortic stenosis-related left ventricular hypertrophy (LVH)." (PMID 40599543, 2025). "By utilizing specifically designed antisense oligonucleotides and AAV9-mediated delivery to induce skipping of both exon 5 and exon 6 of MYBPC3, the study successfully reversed cardiac dysfunction and inhibited left ventricular hypertrophy in the mice." (PMID 39684857, 2024). "Mybpc3-null mice showed left ventricular hypertrophy, dilation, and systolic dysfunction compared to heterozygous and wild-type mice, but no systolic anterior motion of the MV or left ventricular outflow obstruction." (PMID 26819945, 2015). "We investigated the metabolic profiles of mutation carriers with the HCM-causing MYBPC3-Q1061X mutation with and without left ventricular hypertrophy (LVH) and non-affected relatives, and the association of the metabolome to the echocardiographic parameters." (PMID 26267065, 2015).
myocardial infarction (9 papers, 2018 to 2025). Gross necrosis of the myocardium, as a result of interruption of the blood supply to the area, as in coronary thrombosis. "However, in recent years, the “myocardial infarction risk gene” has been identified as the MYBPC3 gene for myosin-binding protein C (MyBPC3), which regulates the function of the heart muscle and protects it from proteolysis." (PMID 40136460, 2025). "MyBPC3 is rapidly released into the blood after myocardial injury and thereby may be a biomarker for the early stages of myocardial infarction." (PMID 40136460, 2025).
Hypertension (8 papers, 2011 to 2025). The presence of chronic increased pressure in the systemic arterial system. "The positive correlation between PCSK9 and MyBPC3 in patients with diagnosed hypertension and the similar direction of changes in the levels of these proteins in other groups of men indicate a significant association between them." (PMID 40136460, 2025). "I propose that several new parameters (NO, cfDNA, MPO, PCSK9, MyBPC3, microRNA, TAS, Pb, and Cd) with prognostic and/or predictive potential should be included in screening to confirm the need for the extensive testing of middle-aged men by healthcare professionals due to the risk of hypertension." (PMID 40136460, 2025). "When CAD patients were divided on the basis of associated phenotypes like diabetes mellitus, hypertension or risk factors like smoking status of the subjects carrying wild type and deleted allele, the MYBPC3 gene deletion did not modulate the risk of CAD due to these phenotypes or factors." (PMID 21915287, 2011).
arrhythmogenic right ventricular cardiomyopathy (6 papers, 2020 to 2025). "The most frequent in the ACMG SFs were gene/disease and frequency TTN DCM (four times); KCNQ1 LQTS (three times); MYBPC3 HCM (two times); TMEM43 arrhythmogenic right ventricular cardiomyopathy (two times); PALB2 HBC (two times); and RYR1 MH (two times)." (PMID 36635046, 2023). "Genes initially attributed to other types of cardiomyopathy, such as MYBPC3 for hypertrophic cardiomyopathy (HCM) and DSP for arrhythmogenic right ventricular cardiomyopathy (ARVC), have been shown to contribute to DCM as well [19, 36, 37•]." (PMID 33040239, 2020).
diabetes (5 papers, 2011 to 2025). "However, Mybpc3−/− mice had mean blood ketone levels around 2.0 mmol/L in both a fed and fasted state, reaching blood ketone levels typically observed in mouse models of ketoacidosis." (PMID 41155405, 2025).
congestive heart failure (4 papers, 2018 to 2024). Failure of the heart to pump a sufficient amount of blood to meet the needs of the body tissues, resulting in tissue congestion and edema. "Of the probands with MYBPC3 p.(Gln1061*), none has had congestive heart failure." (PMID 30235249, 2018).
Myocardial fibrosis (4 papers, 2022 to 2025). "Taken together, these results demonstrated that the MYBPC3 R495Q mutation led to the development of severe myocardial fibrosis and inflammation." (PMID 36357371, 2022). "In conclusion, our studies suggest that MYBPC3 deficiency in cardiac fibroblasts can promote their trans-differentiation into myofibroblasts via NF-κB/TGF-β1/HIF-1α/aerobic glycolysis signal cascade, contributing to premature myocardial fibrosis." (PMID 36357371, 2022). "Two of the patients with a genetic result of VUS (in FLNC, MYBPC3) were found to have myocardial fibrosis on CMR without any explanation other than ApHCM." (PMID 40428316, 2025).
aortic stenosis (3 papers, 2014 to 2025). Aortic valve stenosis is a aortic valve disease caused by the incomplete opening of the aortic valve. "We then investigated the subcellular localization of FHL2 by immunogold labeling in cardiac myofibres on ultrathin sections of ventricular tissue obtained from of a human donor, a patient with aortic stenosis, two HCM patients with a MYBPC3 mutation, and from WT and Hom-KI mice." (PMID 25358972, 2014).
atrial septal defect (3 papers, 2021 to 2025). Interauricular communication is a congenital malformation characterized by a communication between the atrial chambers of the heart. "Here, we report a fatal case of a neonate with HCM and an atrial septal defect (ASD) resulting from compound heterozygous MYBPC3 variants." (PMID 41488457, 2025). "LVNC caused by MYH7 and MYBPC3 mutations often complicated congenital heart diseases (CHD), such as atrial septal defect, ventricular septal defect, Ebstein, tetralogy of Fallot, patent ductus arteriosus, patent foramen ovale, and aortic hypoplasia." (PMID 34819141, 2021).
cardiac arrest (3 papers, 2019 to 2020). Cessation of breathing and/or cardiac function. "Using WebGestalt algorithms, in the present case, the combination of MYBPC3, TTN, ACADVL, and RYR2 increased significantly the likelihood of cardiac arrest." (PMID 32101375, 2020).
Danon disease (3 papers, 2020 to 2025). A lysosomal glycogen storage disease characterized by severe cardiomyopathy and variable degrees of muscle weakness, frequently associated with intellectual deficit. "The dilated phenotype subgroup (P.1–P.10) included all patients with Danon disease, the patient with a homozygous ALPK3 variant, carriers of in-frame deletions in TTN and FLNC, a heterozygous TRIM63 missense variant, and carriers of splice-site variants in MYH7 and MYBPC3." (PMID 41440877, 2025).
glaucoma (3 papers, 2022 to 2025). Increased pressure in the eyeball due to obstruction of the outflow of aqueous humor. "As both MYBPC3 and CELF1 were found to play a role in other cells and diseases, they provide a good reference for further studies on AD and glaucoma." (PMID 36118709, 2022).
left ventricular noncompaction (3 papers, 2022 to 2025). Left ventricular noncompaction (LVNC) is a rare cardiomyopathy characterized anatomically by prominent left ventricular trabeculae and deep intratrabecular recesses causing progressive systolic and diastolic dysfunction, conduction abnormalities, and occasionally thromboembolic events. "A 35-year-old woman who was a homozygous carrier of the p.(Pro1066Arg) variant in the MYBPC3 gene, developed HCM phenocopy associated with left ventricular noncompaction and various degrees of conduction disease." (PMID 35888124, 2022). "These include MYBPC3 mutations in HCM, TBX20 (OMIM: 606061) mutations in left ventricular noncompaction (LVNC), and RAF1 (OMIM: 164760) mutations implicated in HCM associated with Noonan syndrome." (PMID 40507801, 2025).
Marfan syndrome (3 papers, 2019 to 2023). A disorder of the connective tissue. "The highest number of VLP/Ps (n = 94) were reported in both MYBPC3 (MIM: 600,958; definitive for hypertrophic and dilated cardiomyopathies[HCM/DCM]) and FBN1 (MIM: 134,797; definitive for Marfan syndrome), accounting for 60% and 51% of the total reported findings for these genes, respectively." (PMID 30900393, 2019).
RASopathies (3 papers, 2023 to 2024). "Due to the genetic heterogeneity of HCM, a comprehensive panel should be used for screening that covers not only the main sarcomeric culprits (e.g., TNNT2, MYH7, MYBPC3, TNNI3, ACTC), but also other causes including RASopathies, mitochondrial proteins, and glycogen storage diseases." (PMID 37180798, 2023). "These included a pathogenic variant in TAFAZZIN:c.284+5G>A (Barth syndrome), a variant of unknown significance (VUS) in MYBPC3:c.1224-80G>A and 2 compound heterozygous LP variants in LZTR1 (LZTR1:c.1943-256C>T and LZTR1:c1261-3C>G) in a patient with clinical features of RASopathy." (PMID 38586174, 2024).
Skeletal myopathy (3 papers, 2013 to 2024). "Unexpectedly, as MYBPC3 encodes a cardiac specific isoform of MyBP-C, skeletal myopathy has been exceptionally described in association with MYBPC3 variants." (PMID 38836037, 2024). "Mutations in MYBPC3, normally associated with the development of HCM, have also been demonstrated to cause skeletal myopathy, apparently due to expression of mutated cMyBP-C in the skeletal muscle." (PMID 23936073, 2013). "Biallelic PTVs in MYBPC3, TNNI3, MYL2 and MYL3 are associated with severe, early-onset CM phenotypes, which can include additional features such as atrial and ventricular septal defects and skeletal myopathy." (PMID 38666070, 2023).
Stroke (3 papers, 2008 to 2023). Sudden impairment of blood flow to a part of the brain due to occlusion or rupture of an artery to the brain. "MYBPC3 mutations can be associated with cardiac events such as progressive heart failure, stroke and sudden death even at younger age." (PMID 18957093, 2008). "Here we studied the clinical outcome of families with HCM or DCM and mutations in MYBPC3, particularly with respect to adverse events like progressive heart failure, sudden cardiac death and stroke." (PMID 18957093, 2008).